ZEB1 (zinc finger E-box binding homeobox 1)
Diseases named in the same sentence as ZEB1 in open-access papers (continued):
Sharing a sentence is not in itself a finding about the gene and the disease.
cancer (continued). "The increased expression of SNAI1, TWIST, and ZEB1 is thought to be associated with the acquisition of the cancer stem cell (CSC) phenotype, high metastatic potential, and increased resistance to chemo- and radiotherapy." (PMID 34683705, 2021). "Altogether, these findings suggest that modulating PRRX1 alters ZEB1/2 and is accompanied by various cellular phenotypes associated with cancer." (PMID 34496784, 2021). "Highly expressed ZEB1 is associated with malignancy of various cancers, and it plays an important role in cancer transformation." (PMID 34006939, 2021). "EMT also associates with a progressively more cancer stem cell-like phenotype, reported to involve interactions between HIF-1α, ZEB1 and the soluble sCD44 splice variant, implicating hypoxia-regulated alternative splicing in cancer stem cell promotion." (PMID 32536347, 2020). "This study found that ZEB1 associates with Yes associated protein (YAP) to enhance cancer progression and proliferation and induces chemoresistance." (PMID 32664703, 2020). "The key point of progression from early-stage to mid-stage cancer cells is the mutation of TF ZEB1, which cross-talks in two pathways." (PMID 32211020, 2020). "Various publications have also highlighted ZEB1′s association with enhanced viability and invasiveness of cancer cells." (PMID 32664703, 2020). "ZEB1 and the loss of E-cadherin were more commonly observed in metaplastic carcinomas than in other subtypes of breast cancer." (PMID 32961774, 2020). "The impact of inactivation of stromal fibroblast-derived ZEB1 on the recruitment of cancer-associated immune cells and endothelial cells were assessed as well." (PMID 31324807, 2019). "RNA expression of TOP2A, PCNA, SOX2, EZH2, ZEB1 genes associated with cell cycle, cancer cell ‘stemness’, and FOXM1‐FOXO activities was similarly affected in both cases." (PMID 30927552, 2019). "PRMT1 and ZEB1 expression were associated with better cancer-specific survival in patients with ccRCC (p = 0.029; p = 0.009, respectively)." (PMID 31655611, 2019). "Our results demonstrated that the stroma-adjusted expression of one EMT-TF, ZEB1, has a unique inverse association with immune cell abundance and activity in multiple cancer types." (PMID 31780722, 2019). "TGF-β promotes the de-differentiation of human basal breast non-CSCs into CSCs via ZEB1, suggesting that the activation of EMT in cancer cells by TGF-β/ZEB1 is closely linked to the de-differentiation of cancer cells into the CSC state." (PMID 31766574, 2019). "We found that EMT-associated factors including vimentin, Snail, and zinc finger E-box binding homeobox 1 were upregulated in cancer cells overexpressing ERRα/PGC-1α and that transforming growth factor-beta (TGF-β) was induced in T-HESCs in the same conditions." (PMID 31040369, 2019). "Zeb1, a strong inducer of cancer cell invasion and metastasis in animal models, is overexpressed in a large number of human cancer types and is associated with poor prognosis." (PMID 31557902, 2019). "Inhibition of STAT3 prevents EMT-associated changes with the overexpression of MCT2 and ZEB1 in EMT-derived cancer cell lines." (PMID 30671168, 2018). "We conclude that EMT in cancer cells is plastic and linked to inflammatory infiltrate, Tgf-β1 accumulation, and resulting Zeb1 induction at sites of invasion." (PMID 29930325, 2018). "Zeb1 expression in cancer cells was associated inversely with membranous claudin 7 expression (p = 0.010), while relatively strong cytoplasmic claudin 7 expression was associated with increased cytoplasmic Sip1 expression (p = 0.0012)." (PMID 29482498, 2018). "Initial studies of ZEB1 in GBM linked it to similar oncogenic properties that were shown in the previously discussed cancers." (PMID 32309604, 2018). "Three other genes with p9 or p11 missense mutations, ZNF281, ZNF148 (ZBP89), and ZEB1, have also been identified as ZF genes important in cancer onset and progression." (PMID 29953437, 2018).
cancer (continued). "We found that ZEB2 did not always have the same prognostic significance and clinicopathological association as ZEB1, especially when performing subgroup analyses according to cancer type." (PMID 28416756, 2017). "According to a previous report, ZEB1 was associated with cell sensitivity to conventional chemotherapy, including gemcitabine, 5-fluorouracil (5-FU), and cisplatin in cancer cells." (PMID 29245917, 2017). "By reduced representation bisulfite sequencing (RRBS) analysis, we identified neurogenin-3 (Ngn3) as a bona fide target of ZEB1 implicated in the acquisition of cancer cell stemness." (PMID 28903350, 2017). "In 117 cases included in the study, they found that high ZEB1 expression in cancer cells and CAFs was associated with poor prognosis." (PMID 28544627, 2017). "E-Cadherin, Vimentin, ZEB1, and N-Cadherin were introduced as the indicators in cancer progression, and their fluctuations were associated with the E2F3 and HIF-2α change." (PMID 28903320, 2017). "ZEB2 expression is also reported to be associated with poor prognosis of several types of cancer, although less frequently than ZEB1." (PMID 28618162, 2017). "Taken together, the hTERT/ZEB1 complex is associated with cancer invasiveness and metastasis in CRC in vivo." (PMID 26540342, 2016). "During this response, ZEB1 associates with p66Shc promoter and suppresses p66Shc transcription and promotes cancer cells metastasis by bypassing anoikis." (PMID 25837484, 2015). "In summary, we suggest that aberrant increase of ZEB1 expression not only stimulates EMT-associated properties during cancer invasion and metastasis, but also leads to an upregulation of bone metastasis related genes, including BMP-inhibitors." (PMID 25973542, 2015). "ZEB1 has been reported tightly associated with cancer initiation, invasion, chemo-resistance and radio-resistance in various types of cancers." (PMID 26036631, 2015). "By uncovering direct regulation of GLUT3 by the transcription factor ZEB1, our study provides evidence for a tight association between two central characteristics of carcinoma development: EMT and glucose metabolism." (PMID 25097756, 2014). "Our results showed that siRNA inhibition of Zeb1 caused decreased cell viability, migratory and invasive capability of T24 cancer cells." (PMID 23844063, 2013). "Genes with putative miR-200a targeting sequences that have been implicated in cell migration and cancer include Abelson murine leukemia viral oncogene homolog 2 (Abl2), deleted in liver cancer 1 (Dlc1), Eph receptor A7 (EphA7), and Zeb1." (PMID 20957176, 2010). "Interestingly, ZEB1 has been shown to interact with Yes-associated protein (YAP) to become a transcriptional activator in some aggressive cancers." (PMID 41303618, 2025). "EMT is characterized by enhanced cancer cell migration and invasion, typically marked by a loss of epithelial markers, like E-cadherin and a gain of mesenchymal markers such as N-cadherin, vimentin, and transcription factors like ZEB1." (PMID 40969596, 2025). "Thus, cancer cells with high levels of ZEB1 exhibit aggressiveness and cause immunosuppression by inducing exhaustion of CD8+ T cells." (PMID 39362647, 2024). "Moreover, Cyclamen pseudibericum (CP) extracts showed cancer invasion and migration inhibitory effect by associating zinc-finger E-box binding homeobox 1 (ZEB1) mediated epithelial to mesenchymal transition (EMT)." (PMID 39065699, 2024). "ZEB1 has been historically linked to the development of cancer and is required for EMT." (PMID 37924077, 2023). "We subsequently investigated whether targeted ZEB1 repression was associated with a functional reprogramming of the cancer cell phenotype." (PMID 37217832, 2023).
cancer (continued). "In colorectal cancer, adipose-derived exosomes provide cancer cells’ resistance to ferroptosis via promoting the inhibition of ZEB1 and upregulation of antioxidant genes encoding for GPX4 and xCT, which consequently leads to decreased PUFA and lipid ROS levels." (PMID 37568677, 2023). "Evidence has shown that expression of EMT-related genes such as those encoding vimentin, Snai1, and Zeb1 (zinc finger E-box binding homeobox 1) could further increase the risk of cancer cells acquiring a high-grade phenotype." (PMID 36831572, 2023). "Moreover, ZEB1 has been associated with the development of the cancer stem cell (CSC) phenotype through the regulation of miRNAs controlling the expression of stemness transcription factors such as SOX2 and KLF4." (PMID 35682554, 2022). "Conversely, the EHF-LF variant could favour EMT-related cancer progression by stimulating ZEB1 promoter." (PMID 35453848, 2022). "High ZEB1 level is also associated with chemotherapy and radiotherapy resistance of cancer cells, ZEB1 level is higher in docetaxel-resistant cells compared to sensitive cells, and silencing of Zeb1 in docetaxel-resistant cells renders them docetaxel-sensitive." (PMID 37305018, 2022). "ZEB1 expression may also promote resistance to new therapies that target major biological pathways associated with cancer." (PMID 35454770, 2022). "In addition to EMT Zeb1 was shown to contribute to other cancer-associated characteristics such as drug resistance, stemness and cellular senescence." (PMID 36517518, 2022). "Deregulation of Zeb1 activity has been implicated in multiple cancer types and, in these settings, Zeb1 acts as an instigator of the activity of cancer stem cells, a subset of cancer cells driving therapy resistance and metastasis, which ultimately cause fatality." (PMID 33108352, 2021). "Highly expressed ZEB1 shows noticeable associations with the malignancy of various cancers." (PMID 33392180, 2020). "However, other cancer cell line studies linked Zeb1 with transcriptional regulation of DNA damage response genes." (PMID 31968535, 2020). "In addition to participating in the invasion and metastatic dissemination of cancer cells, Zeb1 is implicated in malignant tumor formation, cancer stemness, and resistance to treatment." (PMID 32728068, 2020). "Given the significant inverse association between ZEB1 and E-cadherin across various carcinomas, we also wondered whether ZEB1 was involved in PLAGL2-induced EMT." (PMID 31827238, 2020). "Mounting evidence suggests that ZEB1 and miR-200c reciprocally control their expression through a negative regulatory loop, and miR-200c repression or ZEB1 expression has been associated with a worse prognosis in several carcinomas, such as breast and ovarian cancer." (PMID 32313093, 2020). "Expression of the zinc finger E-box binding homeobox 1 (ZEB-1) is associated with epithelial-mesenchymal transition in carcinoma cells, and thus is important in assessing if PDT might act as a risk factor for promoting metastasis in cells not killed by PDT." (PMID 31968535, 2020). "Moreover, ZNF143 is implicated in the regulation of E-cadherin expression through ZEB1, and the loss of E-cadherin by the ZNF143-ZEB1-linked cascade was shown to be related to cancer cell motility." (PMID 30885238, 2019). "Binding of ZEB1 to the E-box domain and subsequent downregulation of E-cadherin during epithelial to mesenchymal transition has been thoroughly associated with invasion and metastasis in several cancers." (PMID 31767037, 2019). "Importantly, this study identified a novel inverse association between the transcription factor ZEB1 and immune activity in multiple cancer types." (PMID 31780722, 2019).
cancer (continued). "Indeed, in a study on pancreatic ductal adenocarcinoma it was found that high expression of ZEB1 in the cancer cells as well as cancer associated fibroblasts inversely correlated to patient prognosis." (PMID 32309604, 2018). "This has major significance in many cancers, where loss of miR-200 results in elevated levels of ZEB1 promoting the expansion of cancer stem cells, and has led to a widely accepted model in which the downregulation of Zfh1 family is necessary to curb stem-ness." (PMID 29629869, 2018). "This new function of ZEB1 may appear to be inconsistent with the current knowledge that cancer cells are commonly associated with genome instability and that many oncogenes promote, rather than maintain, genome instability." (PMID 29352223, 2018). "In line with this hypothesis, the EMT-TF ZEB1, which is upregulated in several human cancers, directly inhibits ESRP1 expression, thus causing AS changes in the CD44 gene." (PMID 28137272, 2017). "Only ZEB1 was significantly associated with cancer stem cell (CSC) markers." (PMID 28700115, 2017). "Previous studies showed that MALAT-1 promotes cancer progression, mainly through the regulation of gene expression, for example, the epithelial mesenchymal transition associated genes, ZEB1, ZEB2, and Slug and the apoptosis related genes, CASP3, CASP8, BAX, BCL2, and BCL2L1." (PMID 26989678, 2016). "We realized that additional gene mutations may coexist with KRAS or EGFR mutations in cancer cells and may also affect the function of ZEB1." (PMID 27456471, 2016). "Both HIF-1α and ZEB1 have been implicated in cancer metastasis and EMT." (PMID 26057751, 2015). "Snail and ZEB1 (deltaEF1) are predominantly involved in the repression of E-cadherin expression, resulting in epithelial to mesenchymal transition, which has been implicated as the critical event initiating cancer invasion and metastasis." (PMID 25109818, 2014). "Analyses of primary cancers and cancer cell lines from different entities revealed an inverse relationship of ZEB1 and E-cadherin (encoded by the CDH1 gene) expression and a positive correlation between ZEB1 and N-cadherin (encoded by the CDH2 gene) expression." (PMID 23667256, 2013). "In accordance with the cancer stem cell hypothesis, ZEB1 is linked to the expression of stemness-associated factors and tumourigenesis." (PMID 23818228, 2013). "This study, in combination with the work of others, identifies ZEB1 as a potential therapeutic target for strategies aimed at improving uptake of therapeutic adenoviruses and preventing or reversing cancer-associated EMT processes while leaving the tumor suppressive functions of TGF-β unaffected." (PMID 21791114, 2011). "Furthermore, high ZEB1 expression levels are commonly associated with poor prognosis for malignant tumors, which further highlights the important role of this transcription factor in cancer progression and metastasis." (PMID 38139138, 2023). "However, genetic deletion of Zeb1 in PDAC cells also leads to liver metastasis associated with cancer cell epithelial stabilization due to the enhanced collective migration of cancer cells and modulation of the immune microenvironment rather than EMT-MET process." (PMID 37173915, 2023). "Moreover, EMT-inducing ZEB1 promotes cancer cell metastasis and loss of cell polarity." (PMID 36077992, 2022).
cancer (continued). "Although mutations in genes encoding transcription factors that are involved in EMT (Twist, Snail, Slug and Zeb1) are known to be extremely rare in cancer, the activity of these transcription factors is regulated by other genes, mutations in which they can occur more frequently in various cancers." (PMID 33204027, 2021). "Interestingly, forced transition from hybrid E/M to fully mesenchymal state mediated by ectopic expression of ZEB1 was accompanied by the loss of tumorigenicity, implicating that the existence in the extremes of E/M spectrum is unfavorable for cancer cell aggressiveness." (PMID 34063254, 2021). "Importantly, up-regulation of ZEB1 at the post-transcriptional level could be induced by the loss or repression of microRNAs (miRNAs) that selectively target ZEB1 in cancer." (PMID 31092700, 2019). "During EMT, cancer cells lose their cell-to-cell attachment by decreasing E-cadherin expression, due to hypermethylation of the promoter region or transcriptional repression caused by Zinc finger E-box-binding homeobox 1 (ZEB1), ZEB2, Snail, Slug (also known as SNAI2), and TWIST." (PMID 29758011, 2018). "Additionally, ZEB1 is linked to a chemoresistant phenotype in cancer cells." (PMID 29352223, 2018). "High expression of ZEB-1 may further enhance its inhibition of the expression of the E-cadherin gene, causing a decrease in E-cadherin levels and an increase in migration and invasiveness in cancer cells." (PMID 24304617, 2013). "The miR-200a/b–ZEB1/2 DNFL has wide-ranging functions but was first described in human cancer cell lines undergoing epithelial–mesenchymal transition (EMT)." (PMID 41533591, 2026). "The interaction between SNAI1 and ZEB1 is part of a complex network of transcription factors that regulate cell plasticity during cancer progression, and it is commonly observed in various cancers." (PMID 41481650, 2026). "SNAI1, SNAl2 and ZEB1 were overexpressed at mRNA level (16.4-fold, 21.8-fold and 17.2-fold respectively) and protein level in cancer tissue as compared to normal pancreatic tissue." (PMID 41481650, 2026). "Similar Zeb1 fold changes are reported in cancer cell lines with reduced levels of miR-200a/b and in Zeb1200M pancreatic islets." (PMID 41533591, 2026). "Factors like the tumor suppressor DAXX and ROCK2 in pancreatic cancer can modulate ZEB1′s effects, influencing cancer progression and drug resistance." (PMID 39615277, 2025). "ZEB1 mRNA levels in patient samples and cancer cell lines were computationally screened using public datasets." (PMID 40830586, 2025). "Pan-cancer meta-analyses demonstrate that low miR-200 and high ZEB1 expression correlate with EMT activation, enhanced invasion, and significantly worse overall and disease-free survival across multiple tumor types, supported by TCGA-based pan-cancer datasets." (PMID 41462674, 2025). "This extensive list of partners allows ZEB1 to play pleiotropic functions in various biological processes, from embryogenesis to cancer." (PMID 41303618, 2025). "This study investigated the role of E-cadherin and zinc finger E-box-binding homeobox 1 in cancer progression among Iraqi PTC patients." (PMID 40787244, 2025). "Snail and Zeb1 have been suggested as markers for the hybrid/mixed epithelial (E)/mesenchymal (M) state of cancer cells." (PMID 40806166, 2025). "Synthesis of phospholipids containing polyunsaturated fatty acids is increased in cancer cells in the mesenchymal state, probably owing to the core position of ZEB1 in lipid metabolism." (PMID 39827156, 2025). "ZEB1-driven remodeling of the HA network plays a pivotal role in cancer cell migration and invasion." (PMID 40178908, 2025).